CARD9 (caspase recruitment domain family member 9)
Description:
Adapter protein that plays a key role in innate immune response against fungi by forming signaling complexes downstream of C-type lectin receptors. CARD9-mediated signals are essential for antifungal immunity against a subset of fungi from the phylum Ascomycota. Transduces signals in myeloid cells downstream of C-type lectin receptors CLEC7A (dectin-1), CLEC6A (dectin-2) and CLEC4E (Mincle), which detect pathogen-associated molecular pattern metabolites (PAMPs), such as fungal carbohydrates, and trigger CARD9 activation (By similarity). Upon activation, CARD9 homooligomerizes to form a nucleating helical template that recruits BCL10 via CARD-CARD interaction, thereby promoting polymerization of BCL10 and subsequent recruitment of MALT1: this leads to activation of NF-kappa-B and MAP kinase p38 (MAPK11, MAPK12, MAPK13 and/or MAPK14) pathways which stimulate expression of genes encoding pro-inflammatory cytokines and chemokines. CARD9 signaling in antigen-presenting cells links innate sensing of fungi to the activation of adaptive immunity and provides a cytokine milieu that induces the development and subsequent of interleukin 17-producing T helper (Th17) cells. Also involved in activation of myeloid cells via classical ITAM-associated receptors and TLR: required for TLR-mediated activation of MAPK, while it is not required for TLR-induced activation of NF-kappa-B (By similarity). CARD9 can also be engaged independently of BCL10: forms a complex with RASGRF1 downstream of C-type lectin receptors, which recruits and activates HRAS, leading to ERK activation and the production of cytokines (By similarity). Acts as an important regulator of the intestinal commensal fungi (mycobiota) component of the gut microbiota. Plays an essential role in antifungal immunity against dissemination of gut fungi: acts by promoting induction of antifungal IgG antibodies response in CX3CR1(+) macrophages to confer protection against disseminated C.albicans or C.auris infection. Also mediates immunity against other pathogens, such as certain bacteria, viruses and parasites; CARD9 signaling is however redundant with other innate immune responses (By similarity). In response to L.monocytogenes infection, required for the production of inflammatory cytokines activated by intracellular peptidoglycan: acts by connecting NOD2 recognition of peptidoglycan to downstream activation of MAP kinases (MAPK) without activating NF-kappa-B (By similarity).
Synonyms: hCARD9; CANDF2; IMD103
Tractability: Small molecule: a structure with a bound ligand is known. Antibody: its Gene Ontology location is reachable by antibodies, with high confidence. PROTAC: UniProt records ubiquitination sites on it; ubiquitination databases record sites on it; its protein half-life has been measured.
Gene: Protein-coding gene on chromosome 9 (136,363,956 to 136,373,683, reverse strand). Ensembl gene ENSG00000187796.
Subcellular location: Cytoplasm
Pathways (Reactome):
Immune System: CLEC7A (Dectin-1) signaling; NOD1/2 Signaling Pathway
Gene Ontology:
Molecular function: CARD domain binding; protein binding; protein homodimerization activity; signaling adaptor activity
Biological process: antifungal innate immune response; apoptotic signaling pathway; host-mediated modulation of intestinal microbiota composition; immunoglobulin mediated immune response; neutrophil mediated immunity; positive regulation of canonical NF-kappaB signal transduction; positive regulation of cytokine production; positive regulation of granulocyte macrophage colony-stimulating factor production; positive regulation of interleukin-17 production; positive regulation of interleukin-6 production; positive regulation of JNK cascade; positive regulation of stress-activated MAPK cascade; positive regulation of T-helper 17 type immune response; protein homooligomerization; positive regulation of cytokine production involved in inflammatory response; positive regulation of ERK1 and ERK2 cascade; regulation of canonical NF-kappaB signal transduction; regulation of immune response; signal transduction; positive regulation of chemokine production; regulation of apoptotic process; response to aldosterone
Cellular component: CBM complex; cytoplasm; protein-containing complex; cytosol; plasma membrane
Genetic constraint (gnomAD): Loss-of-function variants: 53 observed, 58.3 expected, observed/expected ratio (o/e) 0.91, 90% interval 0.73 to 1.14. The synonymous counts are far from expectation, so gnomAD's model fits this gene poorly and the ratio says little. Missense variants: 769 observed, 701.99 expected, observed/expected ratio (o/e) 1.1, 90% interval 1.03 to 1.16. Synonymous variants: 387 observed, 302.9 expected, observed/expected ratio (o/e) 1.28, 90% interval 1.17 to 1.39.
Homologues: Orthologues: chimpanzee CARD9 (99% identical), macaque CARD9 (97% identical), dog CARD9 (87% identical), rat Card9 (86% identical), mouse Card9 (86% identical), pig CARD9 (84% identical), guinea pig CARD9 (81% identical), tropical clawed frog card9 (53% identical), zebrafish card9 (47% identical). Paralogues in human: CARD11 (42% identical), CARD10 (37% identical), CARD14 (28% identical).
Diseases named in the same sentence as CARD9 in open-access papers:
CARD9 is named in the same sentence as 169 diseases in open-access papers, as found by Europe PMC text mining. Sharing a sentence is not in itself a finding about the gene and the disease. The quoted sentences say what the papers report.
fungal infections (81 papers, 2011 to 2026). "Nearly 100 individuals have been identified who carry deleterious biallelic germline variants in CARD9 and experience life-threatening, invasive fungal infections caused by Ascomycetes but are otherwise resistant to other infectious agents." (PMID 42018653, 2026). "In recent years, the number of reported cases of fungal infections associated with CARD9 deficiency has been gradually increasing." (PMID 40740345, 2025). "One article reviewed 27 patients with invasive mycoses caused by various CARD9 mutations, primarily young individuals with a mean age of 22.1 years old." (PMID 41041311, 2025). "This demographic pattern suggests a genetic susceptibility, possibly tied to CARD9 deficiency reported in Asian patients with severe fungal infections." (PMID 40725051, 2025). "Meanwhile, fungal infections in CARD9-deficient patients showed a tendency toward severe invasiveness." (PMID 40740345, 2025). "Recent studies have highlighted a strong association between caspase recruitment domain-containing protein 9 (CARD9) deficiency and susceptibility to dematiaceous fungal infections, particularly phaeohyphomycosis." (PMID 41190069, 2025). "The deficiency of CARD9 renders individuals vulnerable to numerous fungal infections, including Cryptococcus neoformans, Cryptococcus verrucosus, Aspergillus, Pneumocystis, Mucor irregularis, Rhizopus arrhizus, among others." (PMID 41041311, 2025). "In recent years, the number of reported cases of fungal infections associated with CARD9 deficiency has been increasing." (PMID 40740345, 2025). "We and others have shown that mice with CARD9 deficiency are significantly susceptible to fungal infections." (PMID 39745390, 2025). "Trauma and immune deficiency, including chemotherapeutic agents, malignancies, transplant anti-rejection drugs, AIDS, and CARD9 deficiency, are the main triggers for the onset of subcutaneous mycoses." (PMID 40171159, 2025). "This underscores the importance of adequate antifungal therapy and long-term follow-up for patients with CARD9 deficiency-related fungal infections." (PMID 40740345, 2025). "In clinical practice, it is widely believed that CARD9 deficiency is primarily associated with fungal infections, affecting various parts of the body, such as the skin, lungs, central nervous system, urinary tract, and others." (PMID 41041311, 2025). "Understanding the clinical features of patients with CARD9 deficiency-related fungal infections is of great significance for early diagnosis, appropriate treatment, and improving patient prognosis." (PMID 40740345, 2025). "This study retrospectively analyzed 82 patients with CARD9 deficiency complicated by fungal infections and found significant differences in clinical symptoms, fungal pathogens, and gene mutation sites." (PMID 40740345, 2025). "CARD9 deficiency can cause an impaired immune response to fungal infections and result in refractory severe infection or resurgence." (PMID 40171159, 2025). "CARD9 deletion results in impaired fungal killing ability of myeloid cells, causing a systemic fungal infection." (PMID 38566195, 2024). "The signalling axis of β-glucan, DECTIN-1, SYK and CARD9 is a central pillar of inflammasome activation, as well as the release of inflammasome/pyroptosis-associated IL-1β and IL-18 in fungal infection and beyond." (PMID 38515333, 2024). "In humans, CARD9 loss-of-function mutations are closely linked to susceptibility to fungal infections." (PMID 38566195, 2024). "There are currently 29 deleterious CARD9 mutations described in human patients with chronic and severe mycoses." (PMID 38921395, 2024). "While CARD9 deficiency is thought to cause increased susceptibility to fungal infection in human patients, only a few MAC-infected dogs with the CARD9 variant identified in this study had concurrent fungal infections." (PMID 38710903, 2024).
fungal infections (continued). "Increased susceptibility to fungal infections has been associated with variants in CARD9 in human patients (OMIM: 212050)." (PMID 38710903, 2024). "The importance of this signaling pathway in the antifungal response is demonstrated by human Card9 mutations and deficiencies that manifest spontaneous fungi infections across multiple tissues and organs." (PMID 37513967, 2023). "Patients with CARD9 deficiency have impaired cytokine and chemokine production in response to fungal infections." (PMID 38022599, 2023). "We reviewed the literature for reports of fungal infections occurring in patients with AR CARD9 deficiency and found 17 reports of phaeohyphomycosis in patients originating from China, Germany, Angola, Iran, Colombia, Japan, Argentina, and Morocco." (PMID 35628702, 2022). "We showed that, besides host immune responses, fungal specificity is also closely involved in shifting the clinical phenotype in CARD9 deficient patients with dematiaceous fungal infections." (PMID 36159827, 2022). "In the past decade, mutations in CARD9 have been found to be the cause of various fungal infections." (PMID 36159827, 2022). "It is considered that CARD9 deficiencies are prone to causing phaeohyphomycosis in dematiaceous fungal infections, since the defective host immune responses favor fungal growth in the mycelium form in tissue instead of sclerotic bodies." (PMID 36159827, 2022). "Card9-deficient mice are susceptible to various fungal infections, such as C. albicans, Aspergillus fumigatus, and Cryptococcus neoformans, subsequently undergoing an increased tumor load in Card9−/− mice." (PMID 35633725, 2022). "Phaeohyphomycosis has been reported in CARD9 deficiency, a primary immunodeficiency disorder characterized by severe fungal infections that involve predominantly the oral mucosa, subcutaneous tissues, and brain." (PMID 36377664, 2022). "It was shown that CARD9 plays a critical role in the control of fungal invasion by recruiting neutrophils into the CNS, knowing that CARD9-deficient humans develop fungal infections targeting the CNS." (PMID 34682276, 2021). "CARD9–deficiency neutrophils display an increased susceptibility to fungal infection that primarily localize to the central nervous system, subcutaneous, and skin tissue." (PMID 33488294, 2021). "Some findings have demonstrated that CARD9 deficiency gives rise to susceptibility to invasive fungal infection in the brain." (PMID 33488294, 2021). "In this report, we describe an infant with CARD9 mutation combined with TM infection in order to raise clinicians’ awareness of CARD9 mutations as a possible cause of vulnerability to fungal infections." (PMID 34234782, 2021). "The gut commensal microbiota contains a complex population of microorganisms, and CARD9 deficiency in IBD patient results in their being highly predisposed to fungal infections." (PMID 31696662, 2020). "For example, loss-of-function mutations in CARD9 were discovered by studying an extended family with a history of fungal infection." (PMID 32185141, 2020). "CARD9 autosomal recessive defects is associated with increased susceptibility to fungal infections, including, but not limited to, greater susceptibility to chronic mucocutaneous candidiasis, phaeohyphomycosis, and dermatophytic disease." (PMID 31911495, 2020). "Of note, in humans, rare SNPs in CARD9, that lead to truncated or missense mutations in the CARD9 protein (C-terminal tail), have been linked to increased susceptibility to fungal infections and IBD, respectively." (PMID 31813764, 2020). "The immune deficits that render patients with CARD9 deficiency susceptible to fungal infection are discussed at length below, in the section on “idiopathic” infections by Candida spp." (PMID 32185141, 2020). "CARD9 is an essential signaling protein for fungal immunity: homozygous loss-of-function CARD9 mutations cause severe mycoses." (PMID 31396143, 2019).
fungal infections (continued). "CARD9 deficiency in both mice and humans results in vulnerability to fungal infection in the CNS, owing to impaired neutrophil accumulation in the fungal-infected CNS, which correlates with the lack of CXC-chemokine induction." (PMID 29449845, 2018). "It was first shown that Card9-deficient (Card9−/−) mice are highly susceptible to fungal infection (Candida albicans) due to their inability to produce proinflammatory cytokines in response to dectin-1 stimulation e.g. by zymosan or C. albicans." (PMID 30429846, 2018). "Even though clinical presentation is highly variable, CARD9 deficiency predisposes uniquely to chronic and invasive fungal infections in otherwise healthy individuals." (PMID 30429846, 2018). "On the other hand, CARD9-deficient patients are predisposed to recurrent mucocutaneous and invasive fungal infections with C. albicans." (PMID 29666621, 2018). "Since 1989, a total of 14 countries reported cases of fungal infections associated with CARD9 deficiency." (PMID 30369919, 2018). "This interpretation of our in vitro findings is supported by a recent paper that suggests CARD9 deficiency also impairs neutrophil function against fungi infection." (PMID 29940016, 2018). "Autosomal recessive deficiency in the caspase recruitment domain containing protein 9 (CARD9) results in susceptibility to fungal infections." (PMID 30369919, 2018). "We analyzed the characteristics, distribution, frequency, and relationship between the genotype of the CARD9 gene mutations and fungal infections among the reported cases." (PMID 30369919, 2018). "Our aim was to evaluate the global frequency, geographic distribution and nature of mutations in patients with CARD9 deficiency associated with fungal infections." (PMID 30369919, 2018). "Biallelic loss-of-function (LOF) mutations in CARD11, MALT1, and BCL10 lead to combined immunodeficiencies whereas the here-discussed CARD9 deficiency predisposes exclusively to fungal infections." (PMID 30429846, 2018). "Subsequently in 2009, autosomal recessive (AR) CARD9 deficiency was identified to be responsible for recurrent superficial fungal infections and central invasion with Candida spp." (PMID 30429846, 2018). "Biallelic CARD9 LOF mutations are associated with a wide range of fungal infections and the here described R70W CARD9 patient cohort displays the same heterogeneity." (PMID 30429846, 2018). "To analyze the role of CARD9 deficiency in fungal infection, we reviewed the literature and identified 60 cases until 2018." (PMID 30369919, 2018). "In the last 3 years, more than 15 missense and nonsense CARD9 mutations have been reported which associate with the development of a wide spectrum of fungal infections caused by a variety of fungal organisms." (PMID 27092298, 2016). "Accordingly, human CARD9 deficiency is associated with the spontaneous development of persistent and severe fungal infections that primarily localize to the skin and subcutaneous tissue, mucosal surfaces and/or central nervous system (CNS)." (PMID 27092298, 2016). "In contrast, CARD9 mutations in humans have thus far only been associated with fungal infections, although Card9−∕− mice have been reported to be susceptible to intracellular bacterial infections in addition to their susceptibility to fungal disease." (PMID 27092298, 2016). "The more recently discovered caspase recruitment domain-containing protein 9 (CARD9) deficiency provided novel insights in the role of this protein in invasive fungal infection and CMC." (PMID 26845151, 2016). "Consistent with the essential roles of the Card9 pathway in host defense, mice or humans with a genetic loss of Card9 function are immunodeficient and highly susceptible to fungal infections." (PMID 22265677, 2012).